TIMP3 (TIMP metallopeptidase inhibitor 3)
Diseases named in the same sentence as TIMP3 in open-access papers (continued):
Sharing a sentence is not in itself a finding about the gene and the disease.
cancer (continued). "Increased methylation rate was significant among the early cancer, advanced cancer, and metastatic lymph node samples compared with normal tissue samples (P < 0.01), confirming that the loss of TIMP3 protein expression was closely related to TIMP3 gene promoter CpG island methylation." (PMID 23819566, 2013). "Interestingly, the intensity of TACE or TIMP3 mRNA tended to be associated with higher tumour stages (T-status) in this group of 57 evaluable carcinomas (P=0.067 or 0.09, respectively)." (PMID 21102583, 2011). "The effects of TIMP3 genetic variants on cancer risks were reported in the literature; however, those studies were based on cross-sectional or case-control study designs, in which differential survival probabilities may have occurred between groups of various genotypes." (PMID 36499314, 2022). "TIMP3 expression was previously associated with metastasis and poor survival in OC, while re-expression of the embryonically expressed, but subsequently repressed cancer antigens may be associated with an immune response caused by decitabine." (PMID 25003579, 2014). "Epigenetic alterations, such as promoter hypermethylation of tumor suppressor genes (e.g., APC, TIMP3, CDH13), can serve as biomarkers to identify patients at higher risk of progression from BE to cancer." (PMID 40149421, 2025). "These interactions (miR-192–ITGB1, miR-30d–TIMP3, miR-143–BRAF) are linked to poor overall survival and enriched in cancer-related pathways involving extracellular matrix remodeling, adhesion, and MAPK signaling." (PMID 41294900, 2025). "We determined the differential expression of the TIMP3 gene in matched normal tissues and different types of malignancies (pan-cancer) through an online search of the GEPIA database." (PMID 41009435, 2025). "TIMP3 emerges as a promising biomarker with potential applications in cancer research and clinical practice, making it a novel target for further investigation." (PMID 41009435, 2025). "Our findings emphasize the multifaceted involvement of TIMP3 in CRC, not only influencing the molecular pathways associated with cancer progression, but also intricately shaping the immune microenvironment." (PMID 41009435, 2025). "Due to promoter methylation and miRNA binding, TIMP3 expression has been observed to decrease in various cancers." (PMID 38542164, 2024). "Krüppel-like factor 4 (KLF4) is a transcription factor that facilitates the transcription of the tumour suppressor TIMP3 by directly binding to the TIMP3 promoter, inhibiting cancer progression in vitro and in vivo." (PMID 38542164, 2024). "Various studies showed that the TIMP3 level in different cancer types was regulated by other molecules, characterised by organ-specific gene expressions." (PMID 38542164, 2024). "Tissue inhibitor of metalloproteinases-3 (TIMP3) have been demonstrated to suppress cancer progression in vitro and in vivo." (PMID 38542164, 2024). "Some studies have indicated that the expression level of TIMP3 is lower in cervical intraepithelial neoplasia and cancer tissues than in normal samples." (PMID 38542164, 2024). "The expression level of the TIMP3 gene can be induced in both ovarian stromal cells and cancer cells by TGFβ-1, which regulates cell proliferation, migration, and differentiation." (PMID 38542164, 2024). "Community 4 members RARB, TIMP3 and CDH13 have been implicated as tumor suppressor gene targets of DNA methylation and epigenetic regulation in cancers." (PMID 39545637, 2024). "This review provides an overview of TIMP3, from its biological function to its effects on various cancers." (PMID 38542164, 2024).
cancer (continued). "We found that apoptosis-related genes URI1, PAK2, PARP1, CLU, and TIMP3 were significantly upregulated in multiple cell populations of cancer cells." (PMID 37124501, 2023). "The objective of the present work was to explore the evolutionary behavior of the expression of MMP -2, 9, 11, and 13 and TIMP-3, from benign prostate tissues to cancer, and their possible contribution to predicting PCa development." (PMID 37108185, 2023). "TIMP3 expression has been altered in many human cancers, i.e., gastric, hepatic, prostate, endometrial, and lung." (PMID 36830984, 2023). "In particular, our data showed that all inhibitors above tested, except TIMP3, are significantly present in higher levels in cancer patients compared to healthy samples." (PMID 36759828, 2023). "The role of TIMP3 SNPs has been analyzed in multiple cancers, however, its impact on survival is still under investigation." (PMID 36682035, 2023). "Co-expression network showed genes closely associated with RAC1 were calculated among which cancer genes such as MUC1, MUC20, CEACAM5, andCCL20 were positively correlated to expression of RAC1 whereas TIMP3 and MGP was negatively correlated." (PMID 37202394, 2023). "TIMP3 expression decreases with pTNM grade and negatively correlates with cancer staging and prognosis." (PMID 36830984, 2023). "Previously reported 4 cancer-specific methylated genes(DAPK, FHIT and TIMP3) were HPV-positive associated OPSCC markers." (PMID 36344942, 2022). "The protective function of TIMP-3 in cancer is complex and exerted by different molecular mechanisms." (PMID 35207132, 2022). "Beyond cancer, impairment of TIMP3 activity is involved in several human pathologies as cardiovascular diseases and retinopathies." (PMID 36503426, 2022). "The current study concluded that ALKBH5 exerted cancer-promoting effects in NSCLC by suppressing CDKN1A (p21) or TIMP3." (PMID 35318440, 2022). "In CRC, low circFNDC3B level has been observed, and circFNDC3B/miR-937-5p/TIMP3 axis contributes to cancer progression." (PMID 36446779, 2022). "Epigenetic regulation of the TIMP3 gene has been reported to be a key mechanism in cancer progression." (PMID 35207132, 2022). "Shedding of adhesion molecules promotes cancer cell migration and invasion and there is growing evidence that inhibition of their shedding by TIMP-3 leads to decreased cancer progression." (PMID 35207132, 2022). "TIMP-3 plays a protective role in cancer, as will be further discussed in the next sections of this review." (PMID 35207132, 2022). "TIMP3 is considered a potential therapeutic target for cancer; studies focusing on normalizing or reactivating the expression of TIMP3 as a potential anticancer therapy have been recently proposed." (PMID 36503426, 2022). "As will be discussed in more detail in Section 5.6, TIMP-3 expression negatively correlates with the progression and prognosis of several human cancers." (PMID 35207132, 2022). "Many of the ECM components that showed differential expression and were highlighted in the hypernetwork analysis, including MMPs, TIMP3, FN1, LAMC1, and COL4A1/6A2, have previously been reported as prognostic or diagnostic markers in different cancers." (PMID 35267606, 2022). "TIMP-3 has a number of unique features among TIMPs, including the ability to promote apoptosis, as was shown in a number of cancer cells." (PMID 35207132, 2022). "TIMP3 was previously established to be lowly expressed in NPC tissues, and TIMP3 methylation is a common occurrence in many cancers." (PMID 36061358, 2022). "For instance, TIMP-3 has been shown to block E-cadherin shedding and cancer progression in a mouse model of skin tumour." (PMID 35207132, 2022). "Based on the TCGA-LUSC cohort, a high percentage of cancer associated fibroblasts and COL1A1, COL3A1, POSTN1 and TIMP3 expression was also associated with resistance to immunotherapy." (PMID 35480306, 2022).
cancer (continued). "A highly studied gene, TIMP3, which plays a key role in cancer development and progression, was also found to be hypermethylated." (PMID 33918195, 2021). "Transgenic overexpression of TIMP-3, as well as treatment with the purified protein, reduced cancer progression in vivo." (PMID 33673623, 2021). "In conclusion, TIMP3 has been shown to play a role in inhibiting cancer progression in numerous studies." (PMID 34781885, 2021). "And the survival analysis also indicated that TIMP3 was correlated with the overall survival rate of KIRC patients which further reinforce the relationship of TIMP with cancers." (PMID 33750388, 2021). "The authors confirmed TIMP3 as a miR-221/222 target in HCC-derived cancer cells and showed that as a consequence of miR-221-mediated TIMP3 degradation, these cells were resistant to treatment with TNF-related, apoptosis-inducing ligand (TRAIL)." (PMID 32717951, 2020). "Endogenous inhibitors of matrix metalloproteinases (MMPs) play an important role in extracellular matrix (ECM) homeostasis and deregulate ECM remodeling which contributes to cancer growth, migration, and invasion, while TIMP3 can inhibit the function of MPPs." (PMID 32724322, 2020). "The purpose of this study was to investigate potential associations among TIMP-3 genetic polymorphisms, EGFR statuses, and cancer clinicopathologic development in patients with LADC." (PMID 33126605, 2020). "miR-221 and/or miR-222 can attack TIMP-3, inducing drug resistance and facilitating cell growth in different types of cancer through ADAM10- and ADAM17-dependent signaling." (PMID 33419373, 2020). "We have shown that endogenous TIMP‐3 knockdown reverses the inhibitory effect of mAb NJ001 on cancer cell invasiveness, which indicates thatTIMP‐3 is a key regulator of the antimetastatic function of mAb NJ001." (PMID 32744429, 2020). "It was previously reported that the miR-17-5p/3p pair cooperatively regulates TIMP3, a member of the proteoglycans in cancer pathway." (PMID 32080184, 2020). "The protein levels of MMP12, MMP9 and TIMP3 are increased in cancer cells compared to controls after 48 h culture." (PMID 32171282, 2020). "In contrast to TIMP-1 upregulation, there is overwhelming evidence for the occurrence of TIMP-3 silencing in multiple human cancers." (PMID 33419373, 2020). "Decreased TIMP3 expression has been observed in many human cancers, i.e., LC, gastric, hepatic, prostate, and endometrial cancer." (PMID 31921636, 2019). "The TIMP3 expression was significantly decreased in cancer tissue in comparison to NLNT (p = 0.01; Wilcoxon test)." (PMID 31921636, 2019). "A similar tendency was also observed in the analysis of data from the Genomic Data Commons, where TIMP3 was significantly decreased in cancer tissues in comparison to controls in both analyzed AC and SCC cohorts." (PMID 31921636, 2019). "Next, we used lentiviral transduction system to establish two TIMP3 knockdown stable clones of HCT116 to further examine the role of TIMP3 in MPT0B390-inhibited cancer cell migration." (PMID 31588243, 2019). "The validation of expressional data with the Genomic Data Commons also revealed significantly decreased TIMP3 level in cancer tissues in comparison to controls in both LUAD (p < 0.001; UMW) and LUSC projects (p < 0.001; UMW)." (PMID 31921636, 2019). "It was previously demonstrated that restoring TIMP3 function by blocking the expression of its suppressor gene EZH2 (using RNA interference) led to subsequent inhibition of cancer cell migration." (PMID 31921636, 2019). "Our analysis found TIMP3 expression to be significantly lower in cancer tissue than in normal looking neighboring tissue." (PMID 31921636, 2019). "While, TIMP3 expression was decreased both in cancer tissue and NLNT, with significantly lower expression in cancer." (PMID 31921636, 2019).
cancer (continued). "TIMP-3 has been another important target of study regarding the inhibition of cancer cell migration, invasion, and metastasis in vitro and in vivo by natural products." (PMID 31921634, 2019). "Firstly, CpG islands in promoter regions of various tumor suppressor genes (TSGs), such as p16INK4A, p73, BRCA1, and TIMP3, are hypermethylated in cancer, inhibiting their expression and, thus, leading to uncontrolled proliferation of cancer cells." (PMID 30669400, 2019). "These evidences suggest that overexpression of TIMP3 is a rational multi-phenotypic approach for cancer treatment." (PMID 31588243, 2019). "Tissue inhibitor of metalloproteinase 3 (TIMP-3) inhibits ECM turnover and has been associated with cancer." (PMID 32010611, 2019). "Increased cancer secretion of inhibin βA results in elevated Timp3 expression in osteoblasts and the subsequent repression of procollagen processing during osteoblast differentiation." (PMID 30348200, 2018). "In vitro studies using breast and other cancer models have further corroborated the oncogenic role of miR-221/222 by demonstrating TIMP3, PTEN, and PUMA, as putative targets of miR-221/222." (PMID 30214383, 2018). "TIMP-3 expression is often blocked in cancers, thus increased levels of TIMP-3 resulted in better response to chemotherapy." (PMID 29881724, 2018). "TIMP3, known to inhibit metalloproteases, was downregulated in the cancer tissue samples and is known to be a target of miRNAs." (PMID 28886030, 2017). "Overexpression of miR-21 is known to induce EMT by targeting PDCD4 and TIMP3 mRNAs in various cancer types, including ESCC." (PMID 29254151, 2017). "miR-222 can play a role as an onco-miR in some cancer types, such as cervical cancer, prostate carcinoma, since it can target tumor suppressors, such as PTEN, p27Kip1, and TIMP3, promoting the proliferation, migration and invasion of cancer cells." (PMID 27811362, 2016). "Previous reports have shown that miR-21 targeted TIMP3 and decreased its expression in some cancer cells." (PMID 26872030, 2016). "In another study, overexpression of TIMP-3 in HeLa carcinoma cell line induces a FADD-dependent type II apoptotic signaling pathway." (PMID 27659937, 2016). "These target genes include E-Cadherin, TIMP-3, and Slit2, which are responsible for cancer cell proliferation and invasion." (PMID 26484567, 2015). "Other studies have confirmed that other TIMP family members are associated with cancer prognosis, e.g., TIMP-1 and TIMP-3." (PMID 25905787, 2015). "The complex role of Timp3 appears to be similar to the “double-edged sword” of TNF signaling in cancer." (PMID 25807548, 2015). "This microRNA plays a crucial role in the down-regulation of PTEN and TIMP3 in several types of cancers." (PMID 25886619, 2015). "Overexpression of EZH2 confers an invasive phenotype on cancer cells via downregulation of tumor suppressor TIMP-3." (PMID 25153722, 2014). "In a study examining the use of TIMP-3 as biotherapy for CRC, adenovirus-mediated TIMP-3 transduction arrested cancer cell growth and induced apoptosis." (PMID 24518611, 2014). "To date, several therapeutic strategies targeting TIMP-3 have already shown promising effectiveness in cancer treatment." (PMID 25171061, 2014). "The CpG island methylation of TIMP3 was detected in tumor tissues, cancer-adjacent tissues, and lymph nodes with metastasis." (PMID 23819566, 2013). "Cancer cell lines with methylated TIMP3 have reduced TIMP3 expression and are more sensitive to 5-FU than those with unmethylated TIMP3." (PMID 23527119, 2013). "In this regard, we suggest that the vicinity of cancer cells can induce normal fibroblasts to become “active fibroblasts”, which produce higher levels of specific markers, including TIMP3 and COL4A1." (PMID 24039846, 2013). "In the present study we investigated the proapoptotic effect of TIMP3 on the mesenchymal cancer cell line Cal78." (PMID 23894681, 2013).
cancer (continued). "Reduced expression of TIMP-3 protein within cancer cells was correlated with carcinomas of high nuclear and histological grade (p = 0.032 and p = 0.015, respectively), and low ER expression (p = 0.053)." (PMID 17032447, 2006). "With regard to patient outcome, reduced TIMP-3 expression within cancer cells was weakly correlated with reduced recurrence-free survival in the overall patient population by univariate analysis (p = 0.052)." (PMID 17032447, 2006). "TIMP-3 expression has been detected in several cancer types, including esophageal, colorectal, endometrial and prostatic cancer." (PMID 17032447, 2006). "Reduced expression of cancerous TIMP-3 protein was correlated with carcinomas of high nuclear and histological grades (p = 0.032 and p = 0.015, respectively)." (PMID 17032447, 2006). "We found that the concentrations of methylated APC, hMLH1 and TIMP3 were higher in patients with advanced stage cancer." (PMID 15942635, 2005). "This makes the prognosis for patients with cancer that has lost TIMP-3 significantly less favourable than that for patients with cancer that has maintained TIMP-3." (PMID 15467768, 2004). "Northern blot analysis showed five TIMP-3 mRNA transcripts to be present in normal mucosal epithelium and in moderately and poorly differentiated carcinoma." (PMID 9184186, 1997). "Additionally, we used TISMO database analysis to determine the expression of TIMP3 in cancer immunotherapy." (PMID 41009435, 2025). "These functions collectively establish TIMP3 as an inhibitor in diverse cancers, including CRC." (PMID 41009435, 2025). "Thus, the diminished expression of TIMP3 in these cancer patients suggests its potential significance in studying invasion and metastasis, given its crucial role in maintaining extracellular matrix (ECM) homeostasis and inhibiting metastatic processes." (PMID 41009435, 2025). "Furthermore, TIMP3 (Tissue Inhibitor of Metalloproteinases-3) is frequently silenced by promoter hypermethylation in various types of cancer." (PMID 40872531, 2025). "However, further studies are required to confirm the role of TIMP3 in cervical carcinogenesis and cancer progression." (PMID 38542164, 2024). "According to the TCGA data, TIMP3 expression is lower in cancer samples than in normal samples." (PMID 38542164, 2024). "Considering the impact of the shift in the balance of shed versus unshed BG (modified and unmodified), it is worth noting that TIMP3, that we defined here as a regulator BG ectodomain shedding, is also altered in several cancers and has been proposed as a therapeutic target." (PMID 38360757, 2024). "Upregulation of PTEN, P27 and TIMP3 by delivered miRNA‐221 for cancer suppression." (PMID 38919334, 2024). "Various reports have been published regarding the effects of TIMP3 on other types of cancer." (PMID 38542164, 2024). "Moreover, the biological function of TIMP3 and its effects on cancer through its regulation of TIMP3 or related molecules are discussed in this study." (PMID 38542164, 2024). "However, the correlation between TIMP3 expression and cancer progression in EOC remains inconsistent." (PMID 38542164, 2024). "When serous EOC cell dormancy was induced with DOX, TIMP3 expression increased in the cancer cells." (PMID 38542164, 2024). "Cancer patients with decreased TIMP3 expression have poor outcomes." (PMID 38542164, 2024). "TIMP3 may be a useful biomarker for gynaecological cancers and is a potential target for future cancer therapy." (PMID 38542164, 2024). "More importantly, TIMP2 and TIMP3 have been identified as novel biomarkers for cancers." (PMID 36494333, 2022). "Furthermore, as an independent and promising biomarker, TIMP3 plays a regulatory role in a plethora of cancers and is lowly expressed in NPC tissues." (PMID 36061358, 2022). "All of these results reinforced the relationship of TIMP3 with cancers." (PMID 33750388, 2021).